EML4 (EMAP like 4)
Diseases named in the same sentence as EML4 in open-access papers (continued):
Sharing a sentence is not in itself a finding about the gene and the disease.
tumor (continued). "After feeding crizotinib, the tumor volumes of EML4-ALK (V1) and TTC7A-ALK groups were significantly reduced, which indicated that NIH3T3 cells expressing EML4-ALK (V1) and TTC7A-ALK were highly sensitive to crizotinib treatment in vivo." (PMID 40054123, 2025). "The EML4-ALK fusion gene was initially identified by Japanese researchers in the tumor tissue of a male adenocarcinoma patient with a history of smoking." (PMID 40584293, 2025). "Remarkably, an EML4: exon 13–ALK: exon 20 fusion was identified in the tumor sample from P07 at the RNA level." (PMID 38661052, 2024). "The prognostic indicators incorporated for LUSC include Age, EGFR mutation, EML4-ALK translocation, Gender, TNM stage, new tumor event, and Tumor stage." (PMID 39331207, 2024). "One such example is the overexpression of ERBB family of RTK observed in EML4-ALK-positive NSCLC tumours." (PMID 39695132, 2024). "Then, next-generation sequencing on circulating tumor DNA identified multiple ALK mutations, including ALK G1202R, I1171N, ALK-ENC1, and EML4-ALK." (PMID 37007089, 2023). "In various xenograft models using human-derived tumors or tumor cell lines expressing EML4- or NPM–ALK fusion proteins, Crizotinib inhibited tumor growth, decreased proliferation, increased apoptosis, and dose-dependently decreased phosphorylation." (PMID 37375228, 2023). "The targeted next generation sequencing based genomic profiling of the tumor using formalin-fixed and paraffin embedded tissue was performed and a EML4-ALK fusion was detected." (PMID 37950305, 2023). "A major finding of this study is that durable responses to alectinib in the murine EML4-ALK tumor models require a functional adaptive immune system." (PMID 36739466, 2023). "In BaF3 cells expressing EML4–ALK, and these with gatekeeper mutations (G1269S and L1196M), Brigatinib has been shown to induce tumor regression." (PMID 37375228, 2023). "Similar to other tumor types, TPM3::NTRK1, EML4::NTRK3 and ETV6::NTRK3 fusion variants represented the majority of NTRK1–3 translocations identified in this study." (PMID 37686416, 2023). "EML4-ALK gene fusions are oncogenic drivers in non-small cell lung cancer (NSCLC), and liquid biopsies containing EML4-ALK fragments can be used to study tumor dynamics using next-generation sequencing (NGS)." (PMID 37016288, 2023). "The rearrangement of ALK causes pathological activation of the EML4 (echinoderm microtubule-associated-protein-like 4)-ALK complex, leading to alterations in the correct formation of microtubules and the proliferation and migration of tumor cells." (PMID 36836402, 2023). "Given that S1 cleavage in situ localized to cells of the tumor vasculature, we defined marker gene modules for both endothelial and pericyte populations and computed their expression scores across all cells in Eml4-Alk lungs." (PMID 36192379, 2022). "Through a combination of spatial profiling and scRNA-seq analysis, we found evidence suggestive of increased pericyte coverage within the Eml4-Alk tumor vasculature, potentially mediated by altered paracrine signaling via PDGF and CXCL12." (PMID 36192379, 2022). "Qualitatively, while Z7 exhibited broad, diffuse staining throughout Eml4-Alk tumor tissue, Z1 exhibited a prominent spindle-like pattern, suggesting different cells of origin for the proteases cleaving the two probes." (PMID 36192379, 2022). "To this end, we established tumor organoids in vitro by inducing Eml4-Alk fusions in alveolar type 2 (AT2) organoids via CRISPR-Cas939." (PMID 36192379, 2022). "As expected, in another GEM model expressing the EML4‐ALK fusion oncogene with the L1196M mutation (n = 3), substantial tumor regression was also observed within one week of treatment with 40 mg/kg XMU‐MP‐5 twice daily." (PMID 34845836, 2022).
tumor (continued). "The EML4-ALK fusion gene in circulating tumor DNA was significantly correlated with shorter PFS (1.2 months vs. 11.4 months, HR 5.2, p = 0.0153)." (PMID 36612200, 2022). "They demonstrated that giving the TKIs after irradiating the tumour can increase the DNA damage in both EML4-ALK V1 and V3 patient-derived cells." (PMID 35884511, 2022). "In contrast, Eml4-Alk tumor regions exhibited distinct localization of Z1 relative to epithelial cells marked by E-cadherin, while there was diminished Z1 labeling in healthy lungs altogether." (PMID 36192379, 2022). "We obtained NSCLC tumor biopsies from 11 patients with EML4-ALK rearrangements before and/or after ALK inhibitor therapy." (PMID 35999456, 2022). "We here demonstrate that EML4–ALK variant 1 forms condensates via phase separation in human cancer cell lines, murine lung tumors as well as tumor-derived organoids." (PMID 33976114, 2021). "Consecutive tumor re-biopsies performed in patients receiving ALK inhibitors sequentially allowed the molecular basis for tumor evolution in EML4-ALK NSCLC to be determined." (PMID 33922215, 2021). "This combination resulted in a higher tumor burden and an increased number of tumor nodules compared to control Eml4-Alk mice alone." (PMID 34885137, 2021). "We further performed in vivo tumor formation assay in nude mice using NIH3T3 cells with overexpression of wild-type EML4–ALK or the EML4–ALK21S mutant." (PMID 33976114, 2021). "We analyzed the tumor burden of mice 6 weeks after injection with Eml4-Alk adenovirus (Alk–6wks) and compared it to mice that, in addition, expressed Mad2 (Alk+Mad2–6wks)." (PMID 34885137, 2021). "This study suggests that EML4-ALK enhanced the survival of tumor cells and promoted cell proliferation." (PMID 34090412, 2021). "The FISH analysis detected significant differences in the aneuploidy levels in the non-tumor regions of Eml4-Alk+Mad2 compared to Eml4-Alk alone, although both tumor groups presented similar levels of aneuploidy." (PMID 34885137, 2021). "In this study, we established mouse LUAD cells with tumor-initiating ability driven by loss of Cdkn2a and expression of mutant KRAS or EML4-ALK oncogenes." (PMID 33348616, 2020). "This tumor was determined to harbor an EML4-ALK oncogenic gene rearrangement by clinical-grade bulk DNA analysis." (PMID 32822576, 2020). "An AGK‐BRAF fusion was newly identified in postmortem tumor specimens from a donor with a known EML4‐ALK fusion and resistance to ALK inhibitor therapy." (PMID 31747139, 2020). "In our present study, endogenous EML4cc expression reduced EML4-ALK self-assembly and suppressed tumor cell growth in vitro and in vivo, suggesting that overexpression of the EML4-cc domain induced oligomer dissociation of the EML4-ALK protein." (PMID 32300555, 2020). "Platelets can also capture extracellular vesicles (EVs), released by cancer cells, harboring tumor-specific RNA such as tumor-derived EML4-ALK rearranged RNA." (PMID 37362555, 2020). "We found that the cMet:EML4 ratio on population level was close to 1 in all tumours, but on average 6.22% of cells in K and 5.67% of cells in KM tumours carried 3–5 copies of cMet." (PMID 32030896, 2020). "We also demonstrated that exogenous administration of synthetic EML4cc peptides suppressed ALK phosphorylation and tumor cell growth in EML4-ALK positive cells." (PMID 32300555, 2020). "Eight tumor samples from five patients in this cohort were tested by RNA-seq, and five (62.5%) were positive for EML4-ALK fusion; all of these samples were collected before ALK TKI administration." (PMID 32674491, 2020). "The relative EML4 mRNA expression at each exon in NAT specimens was calculated as the ratio of the normalized values with GAPDH mRNA to those in tumor tissues." (PMID 30943926, 2019). "Without any known actionable mutations were detected in the five samples, such as EGFR, KRAS, BRAF, HER2, and EML4‐ALK in the tumor tissues." (PMID 30941903, 2019).
tumor (continued). "Of the four patient’s that had EML4-ALK positive tumours, two of the patient’s had detectable CTC counts (Pt #34, 35)." (PMID 30889898, 2019). "YAP silencing suppressed tumor growth in resistant cells, patient‐derived xenografts, and EML4‐ALK transgenic mice, whereas YAP overexpression decreased the responsiveness of parental cells to ALK inhibitor." (PMID 31633304, 2019). "YAP inhibition suppressed tumor growth in resistant cells, patient‐derived xenograft, and EML4‐ALK transgenic mice, whereas YAP overexpression decreased the responsiveness of parental cells to ALK inhibitor." (PMID 31633304, 2019). "The transcript fusion of EML4 exon 18 to ALK exon 20 was identified in both the patient’s tumor and crizotinib-6 xenografts." (PMID 29764505, 2018). "Initially, first-generation TKIs such as gefitinib (for EGFR-positive NSCLC) and crizotinib (for EML4–ALK fusion-positive NSCLC) demonstrate strong anti-tumor activity; however, most patients develop resistance and subsequently relapse." (PMID 29764505, 2018). "It is noteworthy that a preliminary assessment of tumour uptake of this radiotracer was also carried out in mice bearing subcutaneous human H3122 (EML4-ALK-positive) NSCLC xenografts and evaluated by PET-CT imaging in conjunction with blocking studies." (PMID 28594000, 2017). "The distribution of tumor-derived EML4-ALK fusion fragments and germline DNA fragments was highly similar, demonstrating that genomic DNA released from cancerous cells circulates in plasma as nucleosomal-sized fragments." (PMID 28448587, 2017). "RT-PCR was used to establish exosome-mediated transfer of tumor-derived EML4-ALK rearranged RNA from cancer cells to blood platelets." (PMID 26544515, 2016). "Compared with the EGFR mutation and EML4-ALK rearrangement patients, KRAS mutation patients demonstrated unique features in terms of tumor site, pathology stage and smoking status." (PMID 26739511, 2016). "Injection of EML4-ALK overexpressing 3T3 cells into nude mice induced tumor growth indicating transforming activity of the EML-ALK fusion protein." (PMID 27045755, 2016). "Further, treatment of EML4-ALK-driven brain metastases with PF-06463922 led to regression of tumor volume and prolonged mouse survival, an effect that was reversible upon withdrawal of the inhibitor." (PMID 27483357, 2016). "EML4-ALK fusion transcripts were confirmed by RT-PCR followed by Sanger sequencing in post-treatment tumor samples of patients #1, #2 and #3." (PMID 27045755, 2016). "This suggests that the ALK mutation was gained after duplication of the EML4-ALK fusion or that the mutation is present only in a proportion of the tumor cells, while being wild type in the other tumor cells." (PMID 27045755, 2016). "In patient #1, we confirmed the presence of the EML4-ALK fusion gene in the post-treatment sample taken from a tumor growing under crizotinib." (PMID 27045755, 2016). "Ectopic expression of L1196M and C1156Y leads to resistance to crizotinib in EML4-ALK-transformed Ba/F3 cells, indicating that these tumor-derived L1196M and C1156Y mutations decrease the tumor's sensitivity to ALK inhibitors." (PMID 26802023, 2016). "Recently, it was found that exosome released by cancer cells is capable of transferring tumor-derived EML4-ALK rearrangement RNA to platelets." (PMID 27418132, 2016). "AP26113 induced tumor regression in BaF3 xenograft model expressing EML4-ALK, and EML4-ALK harboring G1269S and L1196M (gatekeeper) mutations." (PMID 25888090, 2015). "The inhibition of tumor derived cell line from our EML4-ALK CRC patient by two separate ALK inhibitors is encouraging and provides pre-clinical rationale for enrolling ALK-rearranged CRC patients onto clinical trials with ALK inhibitor." (PMID 26172300, 2015). "Future studies are required to clarify the biological features of these tumours and investigate the mechanisms underlying the primary resistance to EGFR-TKIs when the EML4-ALK rearrangement is present." (PMID 25788996, 2015).
tumor (continued). "Both crizotinib and entrectinib inhibited the phosphorylation of ALK and its downstream signal molecules, including ERK1/2 and AKT from this EML4-ALK rearranged colon patient tumor derived cell line." (PMID 26172300, 2015). "Growth of a tumor cell line derived from this EML4-ALK CRC patient was inhibited by ALK inhibitors crizotinib and entrectinib." (PMID 26172300, 2015). "Although the inhibition of ALK activity by crizotinib treatment can reduce the stem-like properties of EML4-ALK+ tumor cells, but its efficacy is limited by variable primary response and acquired resistance." (PMID 26517679, 2015). "Aisner and colleagues identified one EML4-ALK CRC tumor out of 236 patient tumor samples (0.4%) using FISH as a screening assay." (PMID 26172300, 2015). "Further studies are required to clarify the biological features of these tumours and to investigate the mechanisms underlying the primary resistance to EGFR-TKIs when the EML4-ALK rearrangement is present." (PMID 25788996, 2015). "In this study, we examined, for the first time, the role of EML4-ALK in stem-like properties of NSCLC tumor cells, which was validated both in vitro and in vivo." (PMID 26517679, 2015). "In this study we searched for HLA-A*02:01- and HLA-A*24:02-restricted epitopes derived from EML4-ALK by screening predicted EML4-ALK-derived candidate peptides for the induction of tumor-reactive CTLs." (PMID 24842630, 2014). "We successfully induced an HLA-A*02:01-restricted peptide-specific CTL clone that demonstrated cytotoxicity for EML4-ALK-positive tumor cells." (PMID 24842630, 2014). "The abundance of EML4-ALK positive cells in tumor tissues was assessed according to the intensities of the RT-PCR products on gel electrophoresis." (PMID 23951022, 2013). "For the 5 patients with weak intensity of the RT-PCR products, which suggested low abundance of EML4-ALK positive cells in tumor tissues, all of them were FISH (-) and only one was IHC 3+." (PMID 23951022, 2013). "In such study ALI should be compared with tumor specific mutations like EGFR, KRAS, EML4-ALK etc. to see which mutations are associated with higher systemic inflammation." (PMID 23530866, 2013). "All of the 8 patients with high abundance of EML4-ALK positive cells in tumor tissues (assessed by the signal intensities of the RT-PCR product), were also have high expression of ALK protein (IHC3+), and positive for FISH, except one failed in FISH." (PMID 23951022, 2013). "Eight of the 13 RT-PCR(+) tumors had strong intensity of the RT-PCR products, which suggested high abundance of EML4-ALK positive cells in the tumor tissues." (PMID 23951022, 2013). "A common occurrence in the FISH analysis of IBC tumors was however the presence of a mild increase in copy numbers of the EML4-ALK signals in a fraction of the tumor cells." (PMID 24156086, 2013). "All of the 8 tumors with strong intensity of the PCR products (suggesting high abundance of EML4-ALK positive cells in tumor tissues) also had high expression of ALK protein by IHC stains and all positive for FISH tests, except one failed in FISH." (PMID 23951022, 2013). "EML4-ALK is identified using fluorescence in situ hybridization (FISH) on tumor pathology or cytology specimens." (PMID 25031935, 2012). "More recently, the inhibition of anaplasic lymphoma kinase (ALK) has been reported to result in tumour shrinkage or stable disease in most patients with NSCLC harbouring EML4-ALK fusion genes, but concerned only 2 to 7% of NSCLC." (PMID 22022511, 2011).
tumor (continued). "However, the clinical benefit is often challenged by the emergence of resistance mechanisms and the complexities of tumor heterogeneity and spatial genomic diversity, exemplified by cases harboring concurrent fusions like EML4‐ALK and TPM3‐ROS1." (PMID 41275415, 2025). "Tumor‐adjacent normal tissue areas were not investigated in the present cohort; only wild‐type, EML4–ALK‐rearranged, KRAS‐mutated, and EGFR‐mutated LUAD samples were compared." (PMID 40621945, 2025). "Here, we sought to better understand a pathway through which the EML4–ALK V3 fusion variant, which promotes rapid metastatic spread in NSCLC, causes cells to adopt a mesenchymal-like morphology typical of migratory and invasive tumor cells." (PMID 38458397, 2024). "Different types of integration of EML4 with ALK or other genes, the presence of a secondary mutation in ALK, and activation of alternative signaling pathways such as EGFR, are the mechanisms by which tumor cells become resistant." (PMID 38234663, 2024). "Subsequently, tumor progressed with an acquired EML4::ALK fusion." (PMID 38438731, 2024). "The EML4–ALK oncogenic fusion protein drives tumour progression in ~5% of NSCLC cases." (PMID 39682703, 2024). "ALK autophosphorylation and phosphorylation of STAT3 are inhibited by aletcinib, also aletcinib could suppress the development of EML4-ALK-positive tumor cells." (PMID 38234663, 2024). "The EML4‐ALK fusion protein is expressed in lung under the transcriptional control of EML4 promoter, and the dimerization domain of EML4 permits unregulated dimerization of the TK domain, persistently activating downstream pathways that lead to tumor formation." (PMID 39681089, 2024). "According to our findings, EML4-ALK V1, V3a and V3b harboring the F1174S mutation are sensitive, rather than resistant, to crizotinib highlighting the complexity of monitoring and understanding resistance mechanisms in the NSCLC tumor landscape." (PMID 38264745, 2023). "Therefore, future studies using human EML4-ALK tumor cells implanted in humanized mice will be important to confirm our present findings." (PMID 36739466, 2023). "However, different next-generation sequencing (NGS) approaches and downstream software solutions have resulted in varying sensitivity for the detection of EML4-ALK in circulating tumor DNA (ctDNA)." (PMID 37016288, 2023). "However, a circulating tumor DNA (ctDNA) sample was obtained the same day which revealed an EML4-ALK fusion gene." (PMID 35350512, 2022). "A few pioneer studies have exemplified fusion-circRNAs (f-circRNAs) derived from tumor-associated chromosomal translocations, such as PML-RARα, MLL-AF9, EWSR1/F LI1, and EML4/ALK1, and these f-circRNAs were circularized by transcribed exons of distinct genes affected by the translocations." (PMID 36613512, 2022). "From these results, we hypothesize that the Eml4-Alk oncogenic rearrangement can initiate tumours in Club and AT2 cells, although late-stage tumours homogeneously express the AT2 cell marker, SPC." (PMID 35931677, 2022). "To verify whether tumour cells contained the Eml4-Alk rearrangement, we checked for the aberrant expression of the Alk region affected by the translocation." (PMID 35931677, 2022). "Our study, using FISH and Sanger sequencing, has found that EML4-ALK variant 1 produced a fused circular RNA termed F-circEA1, which affected tumor proliferation, migration, invasion, apoptosis and cell cycle, and had resistance to the molecularly targeted drug crizotinib in H3122 cells." (PMID 34633654, 2022).